INSR (insulin receptor)
Diseases named in the same sentence as INSR in open-access papers (continued):
Sharing a sentence is not in itself a finding about the gene and the disease.
Insulin resistance (continued). "Mutations in the insulin receptor (INSR) gene are associated with insulin resistance and hyperglycaemia." (PMID 31989990, 2020). "Downstream of receptor activation is JNK, which, when activated, can cause increased Ser/Thr phosphorylation of IRS1/2, reducing their Tyr phosphorylation by the activated insulin receptor and thus causing insulin resistance." (PMID 32183037, 2020). "Adipocyte-specific ablation of the insulin receptor (IR) in mice causes insulin resistance, glucose intolerance and dyslipidaemia." (PMID 32555194, 2020). "Fatty liver is caused by insulin resistance in either liver or adipose tissue, as demonstrated by the fact that adipocyte-specific insulin receptor knockout (FIRKO) mice develop hepatic steatosis." (PMID 33005239, 2020). "HMGA1 deficiency causes insulin resistance and diabetes through impairing the transcription of the insulin receptor gene INSR and of the insulin-like growth factor binding protein-1 (IGFBP-1) genes." (PMID 31963852, 2020). "DAG accumulation causes hepatic insulin resistance through the activation of PKCε that results in phosphorylation of the insulin receptor threonine11160, which in turn leads to the inhibition of insulin receptor tyrosine kinase activity." (PMID 32907986, 2020). "In the meanwhile, a novel heterozygous nonsense mutation in exon 2 of INSR was found in humans in a previous report, which causes type A insulin resistance." (PMID 32859686, 2020). "iPSC lines have been demonstrated to recapitulate many Mendelian diseases, including insulin resistance resulting from severe mutations in the insulin receptor." (PMID 33362275, 2020). "Absence of metabolic dyslipidemia and fatty liver in a patient with severe insulin resistance, as in this patient, is suggestive of a primary INSR mutation." (PMID 32018348, 2020). "It has been also reported that iNOS induction in NAFLD leads to S-nitrosylation of the insulin receptor, thereby causing insulin resistance." (PMID 33187321, 2020). "Insulin resistance is caused by the impairment of insulin receptor-mediated signaling in insulin-sensitive organs, i.e., the liver, adipose tissue, skeletal muscles, brain, and so on." (PMID 33005239, 2020). "Decreased insulin receptor molecules cause insulin resistance and impaired glucose tolerance, and defective insulin receptor tyrosine kinase in skeletal muscle triggers insulin resistant obesity." (PMID 32178449, 2020). "Crosstalk between the UPR and insulin receptor signaling has been shown to cause insulin resistance in type II diabetes." (PMID 33066035, 2020). "Failure of INSR internalization leads to prolonged insulin existence in circulation causing hyperinsulinemia and further aggregates insulin resistance as shown in patients with an arginine to cysteine 252 mutation in INSR." (PMID 31658625, 2019). "It was previously suggested that fetuin-A is involved in insulin resistance by inhibiting the phosphorylation of tyrosine kinase of the insulin receptor and therefore causes a disturbance of insulin signaling." (PMID 31579450, 2019). "Downregulation of INSR has been identified in adipose tissue of both obese animals and patients, which is associated with insulin resistance." (PMID 31658625, 2019). "A gain-of-function mutation in ENPP1 Lys121Gln inhibits insulin receptor activity and causes insulin resistance and accelerates liver fibrosis in a cohort of obese NAFLD patients." (PMID 30642126, 2019). "While this seems at variance with previously published data that employed animal models, most of the studies have employed insulin receptor (INSR)-deficient mice as a model for insulin resistance [49, 50, 51••]." (PMID 31749085, 2019). "It is associated with insulin resistance as it inhibits insulin receptor signaling via suppression of cytokine signaling-3 (SOCS-3)." (PMID 31824900, 2019).
Insulin resistance (continued). "With the distinct characteristic of insulin resistance in T2DM pathology and the impaired INSR internalization occurring in T2DM patients, it is not surprising to anticipate a cause–effect relationship between INSR trafficking and insulin resistance." (PMID 31658625, 2019). "In recent years, a new generation of genetic insulin receptor (IR) knockout mouse models enabled researchers to establish the causal link between adipose tissue insulin resistance and the development of type 2 diabetes." (PMID 31309261, 2019). "PTPN1 found from the network study is linked to the common network pathway and modulates insulin resistance through Jak-Stat, insulin receptor substrates (IRS1 and IRS2) and leptin signaling pathway." (PMID 30674322, 2019). "The mutation identified in the insulin receptor of these cavefish is implicated in at least two known cases of the Rabson-Mendenhall syndrome, a form of severe insulin resistance in humans." (PMID 31686269, 2019). "A rare INSR genetic mutation on p.Ile119Met, leading to mildly impaired receptor recycling, causes severe insulin resistance in patients." (PMID 31658625, 2019). "This review summarizes the regulation of INSR trafficking, the underlying mechanisms under normal conditions, and the altered INSR trafficking under insulin resistance and diabetic conditions." (PMID 31658625, 2019). "Although INSR endocytosis appears to be significantly associated with insulin resistance, the exact mechanisms remain undefined." (PMID 31658625, 2019). "Patients with Glu 460 mutation had impaired insulin dissociation from INSR in endosomes, which led to impaired recycling and severe insulin resistance." (PMID 31658625, 2019). "The aberrant alternative splicing of the insulin receptor has been associated with insulin resistance in DM patients because of the possible different binding affinity and signaling specificity of the two isoforms for insulin." (PMID 30901379, 2019). "In this regard, we next investigated another mechanism of insulin resistance, which is a posttranslational modification of insulin receptor substrates by O-linked N-acetylglucosamine (O-GlcNAc)." (PMID 30832230, 2019). "Bi-allelic INSR mutations produce extreme insulin resistance, clinically described as Donohue or Rabson–Mendenhall syndromes (OMIM #246200 or #262190)." (PMID 29700562, 2018). "The study indicated that the effect of HCD on the development of hepatic insulin resistance is associated with the increased interaction between caveolin-1 and the liver insulin receptor." (PMID 29955245, 2018). "Long-term exposure to a “Westernized” HFD causes sexually differentiated insulin resistance that, among other things, is associated with a reduced insulin receptor-mediated activation of TRPC5 channels in POMC neurons from male but not female guinea pigs." (PMID 29973869, 2018). "The insulin receptor signaling pathway is a major mechanism underlying the development of glucose intolerance and insulin resistance." (PMID 29497383, 2018). "It is caused by the agonistic effect of antibodies against the insulin receptor resulting in significant insulin resistance and paradoxical hypoglycemia." (PMID 30462811, 2018). "Mutations in the tyrosine kinase domain of the insulin receptor are known causes of insulin resistance and severe hyperinsulinemia." (PMID 29972435, 2018). "We believe that in humans obesity causes insulin resistance, but in cavefishes, a P211L mutation in insulin receptor leads to insulin resistance and is at least partially responsible for the obese phenotype." (PMID 30151194, 2018). "Bi-allelic loss-of-function mutations in the INSR gene (encoding the insulin receptor [INSR]) commonly cause extreme insulin resistance and early mortality." (PMID 29700562, 2018). "Glucocorticoids in the blood cause a decrease in the efficiency of insulin receptor signaling pathways in peripheral tissues, resulting in insulin resistance." (PMID 30618599, 2018).
Insulin resistance (continued). "Insulin receptor substrate 1 (Irs1) phosphorylation at serine 307 (which negatively controls tyrosine-phosphorylated Irs1 by insulin receptor associated with insuline resistance) was significantly increased in mesenteric arteries from db/db mice." (PMID 29440699, 2018). "Yet, another Indian study reported the INSR gene SNP (rs1799817) was associated with increased insulin resistance in Indian women with PCOS." (PMID 30596735, 2018). "The signal transduction of insulin receptor in the brain is increased in insulin resistance which in turn is linked to increased brain levels of Aβ1‐40 and Aβ1‐42 (Dineley, Jahrling, & Denner, 2014)." (PMID 30079520, 2018). "For example, in DM, misregulated splicing of the muscle-specific chloride channel (CLNC1) can cause myotonia while that of insulin receptor (INSR) correlates with insulin resistance." (PMID 29463057, 2018). "In turn, hypoxia was only observed when MG was combined (HFDMG group), being associated with impaired activation of the insulin receptor (Tyr1163), glucose intolerance and systemic and muscle insulin resistance." (PMID 28490763, 2017). "Mice with diet-induced Obesity developed hyperglycemia and insulin resistance associated with a reduction in expression of Insulin receptor (INSR)." (PMID 28761062, 2017). "The classic daf-2(e1370) allele encodes DAF-2(P1465S) that aligns with the INSR(P1209A) mutation in a patient with Type A Insulin Resistance (TA IR); this proline residue is on the αF-helix of the tyrosine kinase domain." (PMID 27856697, 2017). "A 29-year-old woman developed an autoantibody to the insulin receptor (type Binsulin resistance), causing extreme insulin resistance and hyperinsulinemia.Testosterone levels were elevated to the adult male range." (PMID 27911591, 2017). "Insulin resistance is partly caused by the absence of insulin receptor signaling, such as down-regulated phosphorylation of AKT protein." (PMID 28820447, 2017). "The daf-2(m596) allele encodes DAF-2(G547S) that aligns with a compound heterozygous patient with INSR(G366R; V28A) mutations resulting in DS—the most severe form of human insulin resistance." (PMID 27856697, 2017). "In the example of Type 2 diabetes, TNF-alpha have been shown to be directly associated with induction of insulin resistance, in part through suppression of the insulin receptor substrate component of insulin receptor signaling." (PMID 29058588, 2017). "A more detailed understanding of the effects of miR-15b on hepatic insulin resistance can be found in “Obesity-induced miR-15b is linked causally to the development of insulin resistance through the repression of the insulin receptor in hepatocytes”." (PMID 29159225, 2017). "Insulin resistance has been associated with aberrant splicing of the insulin receptor, however post-receptor defects in insulin signalling have been suggested and cannot be excluded." (PMID 28915272, 2017). "On one hand, insulin resistance in brains induces memory loss via neuronal insulin receptor substrate inhibition, as well as through mitochondrial and dopaminergic dysfunction." (PMID 27793043, 2016). "There are two syndromes associated with severe insulin resistance, type A and type B. Type A insulin resistance syndrome is a genetic disease resulting from mutations in the insulin receptor gene." (PMID 27142369, 2016). "Some negative evidence in support of this model comes from the observation that humans with loss-of-function mutations in the insulin receptor itself, although showing very severe insulin resistance, are protected from dyslipidemia and liver fat accumulation." (PMID 27899914, 2016). "In adipocytes in vitro, endoplasmic reticulum (ER) stress causes insulin receptor (IR) down-regulation, which accounts for insulin resistance." (PMID 27077005, 2016). "Although surface INSR downregulation is a well-established contributor to insulin resistance, the underlying molecular mechanisms remain obscure." (PMID 27577745, 2016).
Insulin resistance (continued). "Since the olfactory bulb has the brain's highest Insulin Receptor (IRs) density and the fastest insulin transport of any brain region, it is the most susceptible to central insulin-resistance." (PMID 27895577, 2016). "Conversely, ANG II can cause insulin resistance by interfering with the insulin-stimulated insulin receptor signaling." (PMID 27803936, 2016). "Mutations affecting the tyrosine kinase domain of the insulin receptor are known to cause severe hyperinsulinemia and insulin resistance." (PMID 27217259, 2016). "In this study, we bioinformatically focused on miR-135 and two predicted target genes, insulin receptor (Insr) and vesicle associated membrane protein 2 (Vamp2) as the first components in the cascade causing insulin resistance in cells." (PMID 27602317, 2016). "Type B insulin resistance is a rare autoimmune disease characterized by the presence of anti-insulin receptor antibodies, which impair the binding of insulin to its receptor and cause severe insulin resistance (IR)." (PMID 27142369, 2016). "At present, ectopic accumulation of fat in liver and muscle associated with over-nutrition is the best understood causal agent for insulin resistance and type 2 diabetes (via diacylglycerol-induced inhibition of insulin receptor substrate)." (PMID 26910563, 2016). "For diabetic patients, due to low insulin level or insulin resistance, the combining capacity of insulin and insulin receptor is deficient and the effects after combining are limited." (PMID 26246836, 2015). "Palmitic acid causes insulin resistance due to changes in the levels of phosphorylation of the IR and insulin receptor substrate-1 (IRS-1)." (PMID 26083118, 2015). "We see this same phenomenon in patients with insulin receptor mutations and extreme insulin resistance." (PMID 26222846, 2015). "Hypoxia can inhibit insulin receptor activation and trigger the formation of inflammatory cytokines which promote peripheral insulin resistance, while sympathetic activation causes insulin resistance by inducing glycogenolysis and gluconeogenesis." (PMID 25873773, 2015). "Because the INSR isoforms have different functional characteristics, their relative expression ratio has been implicated in the pathogenesis of insulin resistance and T2DM." (PMID 25742416, 2015). "We report a patient with extreme insulin resistance with features of insulin deficiency due to insulin receptor autoantibodies." (PMID 25675382, 2015). "In cases with mutations in exons 17-21, the region that encodes the tyrosine kinase domain of the insulin receptor, have been shown to cause severe insulin resistance and hyperinsulinemia." (PMID 25114673, 2014). "Another pro-inflammatory cytokine, IL-6, is considered to cause insulin resistance in skeletal muscles and liver due to defects in phosphorylation of insulin receptor substrate, causing a decrease in gluconeogenesis and an increase in glycogenolysis." (PMID 24481132, 2014). "In conclusion, a single nucleotide polymorphism in the tyrosine kinase domain of the INSR gene was associated with insulin resistance and atherogenic lipoprotein that have a role in the pathogenesis of PCOS in Iraqi women." (PMID 25114673, 2014). "For instance, a high-fat diet leads to insulin resistance causing the reduced level of serine exopeptidase (Dpp4, Dipeptidyl-peptidase 4), which is known to leaven neuronal insulin receptor function, brain mitochondrial function and cognitive function in rats." (PMID 25423262, 2014). "Donohue syndrome (DS) is a rare and lethal autosomal recessive disease caused by mutations in the insulin receptor (INSR) gene, manifesting marked insulin resistance, severe growth retardation, hypertrichosis, and characteristic dysmorphic features." (PMID 24498630, 2014). "Excessive phosphorylation of serine residues of the INSR and downstream signaling molecules have been identified as a molecular cause of insulin resistance." (PMID 25114673, 2014).
Insulin resistance (continued). "Mutation at this region which encodes the tyrosine kinase domain of the insulin receptor was demonstrated to initiate severe insulin resistance and hyperinsulinemia and considerably associated with PCOS." (PMID 25114673, 2014). "As liver steatosis is commonly associated with insulin resistance, we assessed insulin receptor phosphorylation in liver tissues in vivo." (PMID 24643026, 2014). "The peroxisome proliferator-activated receptor gamma (PPARG) and the insulin receptor substrate (IRS1) genes have been shown to be associated with both insulin resistance and type 2 diabetes." (PMID 24447396, 2014). "NPP1 negatively modulates insulin receptor signalling and has been proposed as a pathogenic factor predisposing to insulin resistance." (PMID 25368121, 2014). "Chronic hyperglycemia-mediated oxidative stress and insulin resistance associated abnormity in insulin/insulin receptor signal pathway are the focus in the current researches." (PMID 24386004, 2013). "The ZnT7 null mice were susceptible to diet-induced glucose intolerance and insulin resistance and this was associated with a decrease in the expression of the insulin receptor, insulin receptor substrate 2 and Akt1." (PMID 24265765, 2013). "For one thing, insulin resistance, resulting in compensatory hyperinsulinemia in type 2 diabetes, is associated with the abnormity of insulin/insulin receptor-mediated signal transduction." (PMID 24386004, 2013). "These cytokines activate inflammatory pathways that terminate in activation of Jun N-terminal kinase-1 (JNK1) and inhibitor of kB kinase (IKKβ), the products of which alter signaling downstream of the insulin receptor and cause insulin resistance." (PMID 23577240, 2013). "TNF-α interferes on insulin metabolism cascade, activating proinflammatory pathways that impair insulin signalling at the level of the insulin receptor substrate proteins, causing insulin resistance." (PMID 23919592, 2013). "Ceramide also modulates many of the insulin signaling intermediates such as insulin receptor substrate, Akt, Glut-4, and it causes insulin resistance." (PMID 23835113, 2013). "Despite severe insulin resistance and compensatory hyperinsulinemia, patients with insulin receptor mutations appear to be protected from fatty liver and atherogenic lipid pattern." (PMID 23766565, 2013). "Here, numerous candidate pathways activated by these stimuli have been shown to cause inhibitory serine phosphorylation of insulin receptor substrate proteins or to induce insulin resistance by other mechanisms." (PMID 23349837, 2013). "Magnesium has been proposed to be functionally related to glucose metabolism through an interaction with tyrosine-kinase activity on the insulin receptor which is associated with the development of insulin resistance and type 2 diabetes." (PMID 23472169, 2013). "Splicing alterations of the muscle chloride channel CLCN1 are suggested to be responsible for the myotonia, whereas aberrant splicing of the insulin receptor INSR gene is thought to cause insulin resistance in DM patients." (PMID 23754947, 2013). "Some studies showed that there was a positive association between depressive disorder and insulin resistance due to dysregulation of insulin secretion or insulin receptor signaling." (PMID 22348066, 2012). "Further to β-cell dysfunction and insulin secretory deficit in diabetes, defects in insulin receptor (InsR) expression or function can cause insulin resistance and diabetes mellitus." (PMID 23213296, 2012). "Insulin receptor gene (INSR) mutations are linked to several syndromes of generalized insulin resistance." (PMID 22996131, 2012). "To investigate the mechanisms underlying these findings, we examined a mouse model of insulin resistance in β-cells – which also exhibits reduced β-cell mass, the β-cell-specific insulin receptor knockout (βIRKO)." (PMID 22140505, 2011).